CD44 (CD44 molecule (IN blood group))
Diseases named in the same sentence as CD44 in open-access papers (continued):
Sharing a sentence is not in itself a finding about the gene and the disease.
osteoarthritis (28 papers, 2012 to 2025). A noninflammatory degenerative joint disease occurring chiefly in older persons, characterized by degeneration of the articular cartilage, hypertrophy of bone at the margins and changes in the synovial membrane. "This encoded ezrin protein is known to interact with CD44, a significant contributor to osteoarthritis progression." (PMID 40406113, 2025). "CD44 has been clearly associated with the development of a number of diseases, such as cancer, vascular diseases, tissue fibrosis, and degenerative joint diseases." (PMID 37895896, 2023). "On the other hand, it has been shown that CD44 plays a role in stimulating TLR2 downstream targets with a subsequent progression of osteoarthritis as evidenced by the upregulation of NFκB-, IL-1B- as well as TNFA gene expression in human macrophages." (PMID 37234812, 2023). "Increased ST3GAL4 expression responding to the NF-κB pathway resulted in sialylated CD44 expression, exacerbating osteoarthritis in a mouse model." (PMID 37398192, 2023). "Presently, the Clue repurposing database has shown that hyaluronic acid used for osteoarthritis and interstitial cystitis can be used to target CD44." (PMID 35456223, 2022). "One report by Qadri and colleagues has highlighted a role of CD44 as a regulator of TLR2 signaling in macrophages in the context of osteoarthritis." (PMID 35992852, 2022). "Although the role of HA in the pathophysiology of osteoarthritis is complex, CD44-mediated effects of HA are shown to mainly contribute to the potential mechanism." (PMID 35683635, 2022). "Hyaluronic acid, for example, is a clinically approved ligand for CD44 and this drug has been administered in the clinic to treat diseases such as osteoarthritis." (PMID 34301218, 2021). "Generally, CD44 and CD105 double-positive cells are rare on healthy synovium, but in experimental animal models of osteoarthritis (OA), the number of CD44/CD90 double-positive pluripotent stem cells with high proliferation capacity will increase significantly." (PMID 32894205, 2020). "In patients with osteoarthritis both immunohistochemistry and transmission electron microscopy allowed us to note a higher number of CD44 positive satellite muscle cells forming syncytium." (PMID 26101529, 2015). "However, Spp1 has been reported to alleviate the progression of osteoarthritis via Cd44 when injected into knee joints." (PMID 39563425, 2024). "For example, data suggest that PRG4 has anti-inflammatory effects (e.g. decrease in expression of a number of pro-inflammatory cytokines and matrix remodelling enzymes, in a CD44 and toll-like receptor 2- and 4-dependent manner) with implications for osteoarthritis, rheumatoid arthritis and gout." (PMID 31361756, 2019). "However, in osteoarthritis, activation of TLR2 and TLR4 induce IL-1β and TNF-α release that notably increased CD44 gene expression and protein concentrations in human macrophages, whereas blocking CD44 with anti-CD44 Ab or HA show opposite results." (PMID 34980167, 2022).
pancreatic ductal adenocarcinoma (28 papers, 2016 to 2026). An infiltrating adenocarcinoma that arises from the epithelial cells of the pancreas. "Furthermore, a recent study showed that CD44 circulating tumor endothelial cells were associated with poor prognosis in pancreatic ductal adenocarcinoma after radical surgery." (PMID 34820420, 2021). "It has been reported that miRNA-21 modulates key stemness factors in pancreatic ductal adenocarcinoma, including CD44, CD133, and ALDH1, with miRNA-21 knockout significantly downregulating these factors." (PMID 39851519, 2025). "As to the function on stems cell or CSCs, recent studies have shown that KLF4, as a negative regulator of CD44, has the function of inhibiting the characteristics of cancer stem cells in pancreatic ductal carcinoma." (PMID 39695175, 2024). "For instance, HA binding to CD44 recruits RTKs, which in turn promotes cell survival and migration, conferring poor prognostic in pancreatic ductal adenocarcinomas." (PMID 34944493, 2021). "In pancreatic intraepithelial neoplasia and pancreatic ductal adenocarcinoma, CD44 is central in promoting the upregulation of EMT biomarkers expression, Snail1 and Zeb1, as well as stimulating migration and invasion." (PMID 34944493, 2021). "CD44 knockdown using CD44 shRNA in pancreatic ductal adenocarcinoma cells not only efficiently reduced the expression of Zeb1 and Snail1 but also significantly impaired cell proliferation and invasion." (PMID 34944493, 2021). "In this study, we investigated the effect of BRM270 on the isolated CD44 positive pancreatic ductal adenocarcinoma cells (CD44+ PDAC)." (PMID 31049070, 2019). "Co-expressing populations of CD24+/CD44+/EpCAM+/CD133+ with pro-tumorigenic gene expression profile were reported in pancreatic ductal adenocarcinoma." (PMID 30121075, 2018). "Notably, several of the genes affected by Cr(VI) exposure such as MLH1, RAD51, CD44, and Nupr1 are well-recognized contributors to pancreatic ductal adenocarcinoma (PDAC) development." (PMID 42039696, 2026). "In pancreatic ductal adenocarcinoma (PDAC), miRNA-21 has been linked to the regulation of key stemness markers which contribute to cancer cell survival, invasion, and chemoresistance, such as CD44, CD133 and CXCR4." (PMID 39851519, 2025). "In pancreatic ductal adenocarcinoma, CD44 is upregulated in comparison to normal tissues." (PMID 37108193, 2023). "Besides, krüppel-like factor 4 negatively modulated CD44 expression via binding to the CD44 promoter and disturbing gene transcription to restrict metastatic properties in human pancreatic ductal adenocarcinoma cells." (PMID 33303029, 2020). "In addition, the CDCA8 has been proved could promote the proliferation and invasion of pancreatic ductal adenocarcinoma by activating CD44." (PMID 40465781, 2025). "Furthermore, the separation of pancreatic ductal adenocarcinoma (PDAC) cell lines with different CD44 level uncovered a correlation between high CD44 level and enhanced CSC-like properties, including elevated tumorigenicity, clonogenic abilities, and therapy resistance in vivo." (PMID 38455361, 2023). "In PDAC research, CD24 was successfully implemented as one of the stem cell markers (along with CD44 and ESA) in the first animal studies of stemness in pancreatic ductal adenocarcinoma." (PMID 37108193, 2023). "Herein, we investigate the relationship between pancreatic stem cell markers (PCSC markers), CD44, and epithelial-specific antigen (ESA), tumor stroma, and the impact on recurrence outcomes in pancreatic ductal adenocarcinoma (PDAC) patients." (PMID 33836674, 2021). "Surface CD24 has previously been described, together with CD44 and ESA, for the characterization of putative cancer stem cells in pancreatic ductal adenocarcinoma (PDAC), the most fatal of all solid tumors." (PMID 27203385, 2016). "Indeed, CD44+ pancreatic ductal adenocarcinoma (PDAC) cells with an EMT phenotype display increased tumorigenicity and resistance to gemcitabine compared to CD44− cells." (PMID 38612911, 2024).
Arthritis (25 papers, 2005 to 2025). Inflammation of a joint. "Disease severity and recruitment of lymphocytes in animal models of acute asthma, arthritis, and graft-versus-host disease are reduced by antibody blockade of CD44 or CD44 deficiency, as well as by enzymatic depletion of endothelial HA." (PMID 35069598, 2021). "In other words, this study indicates dual functions of CD44 in arthritis, one that causes disease initiation and another that limits disease severity, at least in part by reducing pathology promoting effects of RHAMM." (PMID 25999946, 2015). "CD44 has been implicated in a number of diseases such as cancer, arthritis, interstitial lung disease (ILD), vascular disease, wound healing, and infections by pathogens." (PMID 25954275, 2015). "Recent work in the K/BxN serum-induced model of arthritis demonstrated that antibody-induced thrombocytopenia reduced arthritis, causing us to question whether CD44 antibodies might primarily ameliorate arthritis through their thrombocytopenic effect." (PMID 23785450, 2013). "Small molecules designed to interfere with binding to receptors, such as CD44 or integrins, have shown promising results in experimental models of arthritis and colitis." (PMID 40282293, 2025). "Numerous studies have found anti-CD44 antibody treatment inhibits inflammation in rodent models of arthritis, cutaneous inflammation, multiple sclerosis, vascular leak syndrome, and Parkinson’s disease." (PMID 41282250, 2025). "Administration of anti-CD44 antibodies inhibited inflammation in mouse models of inflammatory bowel disease, collagen- and proteoglycan-induced arthritis, cutaneous inflammation, and IL-2-induced vascular leak." (PMID 39095775, 2024). "Due to various physiological activities of CD44, so far, involvement of this glycoprotein has been shown in a wide range of disorders, including vascular disease, arthritis, infections, and cancers." (PMID 34861820, 2021). "CD44 was shown to play a role in inflammation, as administration of anti-CD44 antibody protected mice from experimental arthritis." (PMID 34796172, 2021). "Genetic deletion of CD44 increases arthritis severity, but blocking RHAMM function attenuates arthritis suggesting that RHAMM possibly compensates for genetic loss of CD44." (PMID 30587175, 2018). "In collagen-induced mouse arthritis, small HA fragments produced by HYALs activated CD44 and induced upregulation of the pro-inflammatory cytokine IL-618." (PMID 29162939, 2017). "We previously reported that a structurally different protein-receptor, hyaluronic acid mediated motility (RHAMM; CD168), compensates for CD44 when CD44 is genetically deleted in the collagen-induced arthritis model." (PMID 26624007, 2015). "The efficacy of anti-CD44 antibodies has been evaluated in murine models of autoimmune and inflammatory diseases including thrombocytopenia and arthritis." (PMID 25954275, 2015). "Studies also revealed that treatment with anti-CD44 mAbs reduced the severity of arthritis in a collagen-induced mouse model for human rheumatoid arthritis (RA) and reduced the diabetic activity in NOD nice." (PMID 25999946, 2015). "An understanding of the relationship between arthritis, thrombocytopenia, and CD44 antibody treatment remains critical for continued development of CD44 antibody therapeutics." (PMID 23785450, 2013). "In contrast, an additional injection of most anti-CD44 antibodies increased the protection against arthritis." (PMID 23785450, 2013). "For example, using anti-CD44 mAb, it could be shown that collagen-induced arthritis was improved in the rat." (PMID 37108355, 2023). "Functional enrichment further supported that the primed genes are heavily involved in inflammatory response, arthritis-promoting functions (Ccl2, Cxcl5, Sphk1) and, interestingly, Wnt pathway (Bmp2, Rspo3, Cd44) and stem cell differentiation (Sox5, Nrp2, Cdk6)." (PMID 35879783, 2022).
Arthritis (continued). "Macromolecular HA–EGCG conjugates undergo targeted internalization by CD44-overexpressing fibroblast-like synoviocytes and subsequently cause H2O2-induced cell death and inhibition of IL-6 secretion, thereby suppressing the progression of arthritis." (PMID 35423998, 2021). "Interestingly, mice incapable of forming HA–HC complexes, or treated with an anti-CD44 antibody, are more resistant to arthritis than wild-type littermates." (PMID 24653726, 2014). "Leukocytes deficient in CD44 do not appear to interact as tightly with these HA complexes, suggesting that reduced adhesion contributes to the delayed onset of arthritis in these animals." (PMID 24653726, 2014). "To our knowledge this is the first study which has examined IM7, KM201, KM114, KM81, 5035-41.1D, and IRAWB14.4 in the same model, and we have shown that all of these CD44 antibodies delayed the onset and reduced the clinical severity of arthritis in this model." (PMID 23785450, 2013). "While CD44 antibody-induced thrombocytopenia may contribute to some of its therapeutic effect against the initiation of arthritis, for established disease there are likely other mechanisms contributing to its efficacy." (PMID 23785450, 2013). "Interestingly, the only upregulated adhesion molecule in the comparison between mice treated with CFA/collagen II and those treated with CFA alone was CD44, supporting a role for CD44 in this early stage of arthritis." (PMID 15987489, 2005). "Indeed, there is considerable published evidence for CD44 involvement in arthritis, although its exact role remains controversial." (PMID 15987489, 2005). "Support for this model comes from studies showing loss or inhibition of CD44 and VLA-4 (very late antigen-4) interactions with their ligands that can reduce leukocyte rolling interactions and inhibit joint inflammation in animal models of arthritis." (PMID 16207337, 2005). "It is possible that the CD44 antibodies used here work by more than one discrete mechanism in arthritis, with different antibodies falling into different classes of effector molecules or that the antibodies may of course all work by different unrelated mechanisms." (PMID 23785450, 2013). "In this sense, we observed a higher proportion of CXCR5+ T cells in the lymph nodes of p110α−/−ΔT in the pre-arthritis stage and an increased expression of the surface markers ICOS, CXCR5 and CD44 in T-cell blasts of p110α−/−ΔT mice." (PMID 34203838, 2021). "We considered whether the higher number of cells observed in p110α−/−ΔT mice in pre-arthritis stage could be due to an increased expression of homing surface markers, such as CXCR5 and CD44, in activated T cells of p110α−/−ΔT mice." (PMID 34203838, 2021). "For example, the presence of CD44 is involved in initiation of arthritis, while the absence of CD44 by genetic deletion in an arthritis mouse model increases rather than decreases disease severity." (PMID 25999946, 2015). "However, some anti-CD44 antibodies (i.e., IM7, IRAWB14.4, 5035-41.1D, KM201, KM114, and KM81), which reduce serum-induced arthritis can themselves induce thrombocytopenia in murine models." (PMID 25954275, 2015). "The fact that two doses of 5035-41.1D increased the protection against arthritis without further decreasing the platelet count supports our interpretation that anti-CD44 treatment does not likely act solely through inducing thrombocytopenia." (PMID 23785450, 2013). "In addition, treatment with a B2 receptor antagonist decreases CD44, CD54, CD11a and CD11b expression in various cell types after arthritis induction in Lewis rats." (PMID 18986535, 2008). "Similar to IM7, KM81 has been shown to reduce the number of granulocytes circulating in the periphery, providing further support for the concept that CD44 antibodies may be treating arthritis by a mechanism that does not rely solely on platelet depletion." (PMID 23785450, 2013).
Arthritis (continued). "However, the relative ability of each CD44 antibody to ameliorate arthritis onset, or clinical severity, did not appear to be closely linked to their ability to induce thrombocytopenia." (PMID 23785450, 2013). "However, 24 adhesion molecules and chemokine/cytokine genes were identified, some of which are known to contribute to arthritis (e.g. CD44 and neutrophil cytosolic factor 1) and some of which are novel in this respect (e.g. CC chemokine ligand-27 and IL-13 receptor α1)." (PMID 15987489, 2005).
esophageal cancer (25 papers, 2011 to 2025). A primary or metastatic malignant neoplasm involving the esophagus. "Previous research has demonstrated that, in esophageal carcinoma, the loss of E-cadherin is linked to the upregulation of CD44." (PMID 40806710, 2025). "In conclusion, we show that CD44 upregulation is associated with the loss of E-cadherin in esophageal carcinoma and that CD44 promotes MMP-9 mediated tumor invasion." (PMID 22069487, 2011). "TDO2 expression has been shown to be associated with CD44 expression in esophageal cancer." (PMID 34174844, 2021). "CD44 has multiple isoforms due to AS, and we observed CD44 exon 12 (CD44v8) skipping in esophageal cancer, resulting in a change in the proportion between CD44v8-10 and CD44s (the standard isoform)." (PMID 40282339, 2025). "We discovered that the knockdown of FOXC1 significantly reduced the expression of CD44, and CD133 at the protein and mRNA levels, subsequently curtailing the proportion of CD44+ cells within esophageal cancer cell lines ECA-109 and KYSE-150." (PMID 38413558, 2024). "N4‐acetylation of lncRNA CTC‐490G23.2 promotes metastasis of esophageal cancer by increasing CD44 isoform‐selective splicing via interaction with PTBP1." (PMID 39640362, 2024). "The downregulation of the stem cell marker CD44 is a hint at an efficient targeting of esophageal cancer stem-like cells (CSCs) and the inhibition of mesenchymal features of EAC cells associated with metastasis formation." (PMID 36982817, 2023). "IGFBP3 mediates the induction of CD44-high cells by suppressing reactive oxygen species (ROS) in the esophageal cancer microenvironment." (PMID 34404882, 2021). "• HER2 and CD44 are potential biological tumor markers in the initial work-up of patients with esophageal cancer." (PMID 33151397, 2021). "CD44 is a cell-surface transmembrane glycoprotein that has been observed to be present in cancer stem cells of esophageal cancer, a subpopulation of cells with the capacity of self-renewal." (PMID 33151397, 2021). "Incorporation of HER2 and CD44 into clinico-radiomic prediction models improved NCRT response prediction in esophageal cancer." (PMID 33151397, 2021). "In vitro, the combination of CD44+/CD24− subpopulation of esophageal cancer cells has shown to be more resistant to NCRT." (PMID 33151397, 2021). "Subsequently, researchers sorted out esophageal cancer stem cells from esophageal cancer cells using the SP cell sorting approach with CD44, SOX2 and Lgr5 as the markers." (PMID 28193907, 2017). "The potential oesophageal cancer stem cell (CSC) markers CD44 and ALDH were present in 11/17 (64.7%) and 13/17 (76.5%) of the samples respectively, and both were present in 9/17 (52.9%) of the samples." (PMID 27736801, 2017). "The relevance of CD44 and its isoforms as a prognostic factor has been studied for patients with several solid tumors including breast, colon, lung, and oesophageal cancer, however its role in OS remains controversial." (PMID 29371972, 2017). "Taken together, our results provide functional evidence of CD44 upregulation in esophageal cancer invasion." (PMID 22069487, 2011). "Conceivably, expression of standard CD44 is dependent on loss of ESRP1 and 2 in esophageal carcinoma." (PMID 22069487, 2011). "We also found that CD44 AS is a common splicing target in esophageal cancer." (PMID 40282339, 2025). "However, the findings of this study supported by literature suggest a potential value of adding pre-treatment HER2 and CD44 status in NCRT response prediction in locally advanced esophageal cancer." (PMID 33151397, 2021). "• Prediction models combining 18F-FDG PET radiomic features with HER2 and CD44 may be useful in the decision to omit surgery after neoadjuvant chemoradiotherapy in patients with esophageal cancer." (PMID 33151397, 2021). "This study indicates that HER2 and CD44 in the initial work-up could be useful biological tumor markers in predicting γpCR to NCRT in esophageal cancer." (PMID 33151397, 2021).